IL17RA (interleukin 17 receptor A)
Diseases named in the same sentence as IL17RA in open-access papers (continued):
Sharing a sentence is not in itself a finding about the gene and the disease.
psoriasis (continued). "Fully human monoclonal antibodies (mAbs) against IL-17 (ixekizumab and secukinumab) and IL-17 receptor A (IL-17RA) (brodalumab) have rapidly reduced clinical symptoms in patients with psoriasis." (PMID 26792955, 2015). "IL-17A and IL-17RA are emerging as effective biologic targets for autoimmune conditions, particularly psoriasis." (PMID 25849644, 2015). "IL-17RA deletion, specifically in keratinocytes, significantly reduces dermatitis, emphasizing its critical role in IL-17A-mediated neutrophil attraction and psoriasis development." (PMID 38892253, 2024). "Few studies on the rs763780 in IL-17F and rs4819554 in IL-17RA gene polymorphisms in psoriasis have been reported until now." (PMID 37239484, 2023). "Considering the potential benefits of small molecules over monoclonal antibodies, the next leap forward in treating psoriasis and PsA might be small molecule modulators targeting IL-17A/IL-17RA." (PMID 37731935, 2023). "Moreover, studies highlight a potential role of IL-17C in psoriasis inflammation as a mediator, where it stimulates Th17 cells through signaling using heterodimeric receptor IL-17RC, which possesses an IL-17RA and IL-17RE unit." (PMID 37298466, 2023). "Furthermore Cmtm4−/− mice were partially protected from IMQ-induced psoriasis to an extent comparable with Il17ra−/− mice." (PMID 36271145, 2022). "Likewise, brodalumab, a monoclonal antibody against the IL-17RA subunit of the IL-17 receptor has been approved for psoriasis and has shown convincing results in psoriatic arthritis." (PMID 36614836, 2022). "Psoriasis patients with a dominant Th17 and Th1-like Th17 subset profile may be benefited from anti-IL-17 and/or anti-IL-17RA treatment." (PMID 35925616, 2022). "Using the imiquimod-induced psoriasis model and the DMBA/TPA-induced skin tumorigenesis model, the present study found that the single knockin mutation of T779A of mouse IL17RA and knockout of mouse IL17RC prevented the development of psoriasis and tumorigenesis in the epidermis." (PMID 36009523, 2022). "In psoriasis, IL-17RA plays a key role in pathogenesis based on: (a) IL-17A, IL-17F, and other IL-17 isoforms are involved in disease development; and (b) IL-17RA is essential for signaling of all IL-17 cytokines but IL-17D, whose receptor has not been identified to date." (PMID 34201664, 2021). "However, the IL-17RA (IL-17 receptor A or CDw217) deletion in keratinocytes fully protects the animals from psoriasis development upon topical application of the Aldara." (PMID 33510592, 2021). "By this unique mechanism, brodalumab binds IL-17RA and inhibits signaling of IL-17 isoforms, in addition to IL-17A and IL-17A/F, providing high efficacy, fast onset of action, and high probability of complete psoriasis clearance." (PMID 34201664, 2021). "Indeed, antagonistic antibodies to IL-17A or IL-17RA have shown a clinical benefit in patients with psoriasis." (PMID 31936879, 2020). "Furthermore, brodalumab, which is a human monoclonal antibody human anti-IL17RA, a pan inhibitor of IL-17A, IL-17F, and IL-25 is currently used in the treatment of psoriasis where shows a complete clearance of moderate-to-severe psoriasis." (PMID 33574815, 2020). "Considering the results for the variant encoding p.Arg381Gln in IL23R gene, we noted that Il-23R and Th17 cytokines are down-regulated after successful therapies and there are monoclonal antibodies directed against IL-12/23p40, IL-17A and IL-17RA which are effective in psoriasis." (PMID 29091937, 2017). "Therefore, our data are in agreement with the role of IL-17RA, IL-17RC, and IL-17RE in psoriasis, but we could highlight a differential expression pattern in the epidermis." (PMID 40243580, 2025). "Furthermore, it is suggested that combinational L-SNA that targets both TNFA and IL17RA simultaneously may mitigate the course of the disease and improve treatment efficiency in severe cases of psoriasis." (PMID 38951806, 2024).
psoriasis (continued). "The high affinity of brodalumab to human IL-17RA blocks the biological activities of the pro-inflammatory cytokines IL-17A, IL-17C, IL-17E, IL-17F, and IL17A/F heterodimer, resulting in inhibition of the inflammation and clinical symptoms associated with psoriasis." (PMID 36232430, 2022). "However, a clinical trial in psoriasis was aborted after several cases of suicide attempts, even though the association between IL-17RA inhibitor and suicidal tendency is still not confirmed." (PMID 32398096, 2020). "Recently, Wang et.al shows that CARMA2 plays a critical role mediating IL-17RA signaling in keratinocytes, and CARMA2 gain-of-function mutations result in constitutively activated IL-17RA signaling, leading to the development of skin inflammation and psoriasis." (PMID 30814996, 2019). "Monoclonal antibodies such as Bimekizumab, Secukinumab, Ixekizumab, and Brodalumab, which inhibit IL-17A or IL-17RA, have received FDA approval for managing psoriasis and psoriatic arthritis." (PMID 40469524, 2025). "IL-17 is known to play a major role in the pathogenesis of psoriasis, and both anti-IL17A and anti-IL17RA antibodies have shown promising results in the treatment of psoriasis." (PMID 40895565, 2025). "Overall, Il17ra L-SNA improved the clinically, histological, and transcriptional features of IMQ-induced psoriasis in a mouse model." (PMID 38951806, 2024). "In the dynamic evolution process of EMT in psoriasis, as the KC marker Krt5 increased, the EMT markers Vim and Zeb2, and the IL-17 signalling pathway marker Il17ra clearly decrease." (PMID 38472183, 2024). "In the analysis of significantly expressed genes between psoriasis and normal skin, IL17RC was considered as the most significantly overexpressed gene among the IL17 family members, followed by IL17RD, IL17RA, IL17F, and IL17RE." (PMID 36009523, 2022). "Brodalumab, a monoclonal antibody with high binding affinity to IL-17 receptor A (IL-17RA), is a treatment modality approved by the FDA for second line and by the EMA for the first line treatment of moderate to severe psoriasis." (PMID 32010143, 2019). "Based on our current understanding of the immunopathogenesis of psoriasis, biologics have emerged that target TNF, IL-12/IL-23p40 subunit, IL-23p19 subunit, IL-17A, and the IL-17 receptor α chain (IL-17RA)." (PMID 29642409, 2018). "Furthermore, as the KC marker Krt5 increased, the EMT markers Vim and Zeb2, and the IL-17 signalling pathway marker Il17ra clearly decreased, which hinted at the existence of EMT in psoriasis and its intimate connection with the IL-17 signalling pathway." (PMID 38472183, 2024). "Additionally, IL-17RA interacts with and transactivates the epidermal growth factor (EGFR), which mediates a complex IL-17A-induced signaling network in psoriasis." (PMID 38892253, 2024). "This was similar to what we observed in the psoriasis model, and we do not know why Il17ra(T779A)-KI alleviates instead of enhancing skin tumors, as predicted by our previous study." (PMID 36009523, 2022). "To investigate the cooperation between IL17 signaling and centriole duplication in epidermal proliferation, we established psoriasis and skin papilloma models in wild type (WT), IL17 receptor A (T779A) knockin (Il17ra(T779A)-KI), and IL17 receptor C knockout (Il17rc-KO) mouse strains." (PMID 36009523, 2022). "However, the group with mild psoriasis (BSA ≤ 20 and DLQI ≤ 10) demonstrated higher levels of expression of IL-17A and IL-17RA." (PMID 34945130, 2021). "Transgenic mice lacking Il17c, Il17ra, or Il17re display a less severe course of imiquimod-induced psoriasis while an overexpression of Il17c in skin keratinocytes lead to spontaneous development of psoriasiform skin lesions." (PMID 32174926, 2020). "Moreover, many molecularly targeted drugs for psoriasis and AD—TNF, IL-12/IL-23p40 subunit, IL-23p19 subunit, IL-17A, IL-17RA, and IL-4Rα—have been developed." (PMID 29642409, 2018).
psoriasis (continued). "Notably, the “Role of IL-17A in Psoriasis” (T2, −log(FDR) = 1.67) pathway was enriched, in which downregulated CXCL3, IL-8, S100A8, S100A9, IL17RA and CXCL1 expression was observed." (PMID 29871627, 2018). "UVB irradiation inhibits IL-17A/TNF-α-induced IL-6, IL-8, and CXCL-1 production in HDFs by decreasing the expression of IL-17RA and IL-17RC on fibroblasts through TGF-β1/Smad3 signaling pathway, which reveals a new mechanism of the therapeutic action of UVB on psoriasis." (PMID 28217129, 2017). "Our results confirm that UVB irradiation inhibits IL-17A/TNF-α-induced IL-6, IL-8, and CXCL-1 production in HDFs by decreasing the expression of IL-17RA and IL-17RC on fibroblasts through TGF-β1/Smad3 pathway, which reveals a new mechanism of the therapeutic action of UVB on psoriasis." (PMID 28217129, 2017). "Similarly, while the observed increase in circulating IL-17A aligns with the expected pharmacology of IL-17RA blockade, no patient-level studies have directly demonstrated receptor-mediated cytokine accumulation in psoriasis." (PMID 41516330, 2026). "However, the knockin of T779A of Il17ra did not affect the hyperplasia of the epidermis in imiquimod-induced psoriasis model, and these changes were not affected by centrinone treatment." (PMID 36009523, 2022). "In addition, participants diagnosed with psoriasis demonstrated lower RQ values for IL-23A and IL-17RA; however, the obtained results were not statistically significant (p = 0.439585 and p = 0.254683, respectively; Mann–Whitney U test)." (PMID 34945130, 2021). "Importantly, in psoriasis, the use of the monoclonal antibody Brodalumab, which inhibits IL‐17RA and does not allow IL‐17AA, AF, FF, C, and E to bind, has already been approved; this approach blocks the related signaling pathways and functions to improve psoriasis." (PMID 41536464, 2026). "Mice lacking IL-17RA or IL-23p19 had significantly reduced level of psoriasis upon exposure to the Aldara cream, especially IL17RA in keratinocytes seems to have an important contribution to psoriasis development." (PMID 36645209, 2023).
colitis (39 papers, 2010 to 2025). Inflammation of the colon. "In a trinitrobenzene sulfonic acid (TNBS)-induced colitis model, Il17ra-deficient mice were protected from colitis, and administration of an IL-17RA fusion protein ameliorated inflammation." (PMID 40901166, 2025). "IL-17RA signaling also induced IL-6 expression, a cytokine previously associated with colitis-associated cancer development." (PMID 29922293, 2018). "Moreover, IL-17A and IL-17RA inhibition have been associated with the breakdown of the intestinal epithelial barrier and exacerbated colitis in Helicobacter bilis-infected mice." (PMID 33654214, 2021). "Experimental studies on mouse models show an exacerbation of colitis following IL-17A or IL-17RA blockade." (PMID 37631384, 2023). "There are four major MIR31 target proteins, Gp130, IL17RA, Axin1, and Lats1/2, with certain probabilities of acting on inflammation and regeneration in colitis." (PMID 36590397, 2022). "Accordingly the application of the IL17RA IgG1 fusion protein in mice with TNBS-colitis significantly decreased colonic inflammation and protected the mice from weight loss." (PMID 33859636, 2021). "Here CECs were selected as the target for IL-17A, as we previously found that, in mice with TNBS-induced colitis, expression of IL-17A in and IL-17RA on CECs was significantly increased." (PMID 24586980, 2014). "In contrast, mice deficient in IL-17RA are largely protected against experimental colitis induced by intrarectal administration of trinitrobenzenesulfonic acid (TNBS), and administration of IL-17RA IgG1 fusion protein attenuates TNBS-colitis in wild-type mice." (PMID 22082127, 2011). "In conclusion, DBK successfully reduced inflammation in DSS-induced UC mice by modulating the IL-6/IL-6R and IL-17A/IL-17RA pathways, as evidenced by alleviated colitis symptoms, decreased pro-inflammatory cytokines (TNF-α, IL-6, IL-1β), and histological improvements." (PMID 40005956, 2025). "Additionally, the substantial proportion of Il17ra‐positive sensory neurons co‐expressing Trpv1 further supports a pronociceptive role for IL‐17 in colitis." (PMID 40827457, 2025). "Mice lacking IL-17RA and IL-22RA1 exhibited high fungal loads in esophagus- and intestinal tract, severe weight loss, and symptoms of colitis." (PMID 38949991, 2024). "Zhang and colleagues could demonstrate by using IL17RA knockout mice in a trinitrobenzenesulfonic (TNBS) induced colitis model that IL17 is essential for the development of colonic inflammation." (PMID 33859636, 2021). "IL-17RA (–/–) mice have been shown to be less susceptible to acute intestinal mucosal injury, and IL-17 (–/–) or the application of an anti-IL-17 antibody can alleviate TNBS induced experimental colitis in mice." (PMID 32766176, 2020). "In this context, a novel class of anti-IL-17RA-targeted ABD-derived blockers can be used for the development of ARS-producing L. lactis strains useful for in vivo suppression of experimentally induced colitis." (PMID 30304852, 2018). "Furthermore, the disruption of IL-17RA signaling in enterocytes reduced the pathology of DSS-induced colitis and IL-17A and -F are known to induce enterocyte expression of antimicrobial peptides and numerous pro-inflammatory cytokines." (PMID 21124903, 2010). "We found that cytokine-neutralization of IL-17A and/or F or a genetic IL-17RA-deficiency did not affect S. Typhimurium colitis, i.e. pathogen colonization of the mLN, degree of intestinal inflammation and the patterns of cytokines induced by 12 h p.i." (PMID 21124903, 2010). "Surprisingly, Tgfb1, Il17ra, Il23a, Il6ra, Ror1, Tnf, Tgfbr2, Ccr2, and Il17c were downregulated by cigarette smoke exposure in TNBS-induced colitis Gpr15−/− mice compared with similarly treated Gpr15+/+ mice." (PMID 40957881, 2025). "In an acute trinitrobenzene sulfonic acid (TNBS)-induced colitis model, the production of CXCL2 in the colon and its severity are reduced in Il17ra–/– mice." (PMID 38312837, 2024).
colitis (continued). "miR-31 reduces the inflammatory response in DSS- and TNBS-induced mice colitis by repressing expression of inflammatory cytokine receptors IL7R and IL17RA." (PMID 35967345, 2022). "Further analysis reveals that the number of proliferative epithelial cells, which characterizes the inflammatory process and the recovery of epithelia in colitis, is mainly determined by the inhibition of MIR31 on IL17RA." (PMID 36590397, 2022). "Consistent with the results of RNA seq, we further found that GA could markedly suppress the proteins expressions of IL‐17RA signaling and downstream signaling (including NF‐κB, MAPK) in colitis mice and intestinal organoids." (PMID 38639442, 2024). "Collectively, these results indicated that GA could target IL‐17RA signaling to inhibit inflammation and restore intestinal barrier function, and then protect against DSS‐induced colitis." (PMID 38639442, 2024). "However, in Abcb1a-deficient mice that also develop enhanced colitis after Helicobacter infection and IL-17RA blockade, co-blockade of IFN-γ did not decrease disease severity, suggesting that increased IFN-γ may not be causative for the enhanced disease observed in the absence of IL-17." (PMID 29910812, 2018). "miR-31 is upregulated in patients with UC and mice with colitis STAT3 and NF-κB activate the transcription of miR-31 in colorectal cancer cells and organoids, and miR-31 prevents the expression of inflammatory cytokine receptors (IL17R and IL17RA) and signalling protein (GP130)." (PMID 39185319, 2024). "Moreover, T-cell intrinsic effect are not ruled out and as suggested in a colitis model, lack of IL-17RA signaling may release IL-17 mediated suppression of T-bet expression facilitating an aberrant Th1 differentiation program independent on other extrinsic signals." (PMID 22577359, 2012).
autoimmune disease (36 papers, 2009 to 2026). A disorder resulting from loss of function or tissue destruction of an organ or multiple organs, arising from humoral or cellular immune responses of the individual to their own tissue constituents. "IL-17 is linked to localized inflammation and pathogenic in certain autoimmune diseases, in which IL-17 binds to its canonical receptor IL-17RA and activates TRAF6 and the subsequent signaling cascade." (PMID 37270623, 2023). "IL-17/IL-17RA signaling exerts a pathogenic role in multiple inflammatory and autoimmune diseases and targeting this signaling is a remarkable strategy in the treatment of autoimmunity." (PMID 37834058, 2023). "Interleukin 17A and its receptor IL17RA play a pathogenic role in many inflammatory and autoimmune diseases and IL17RA contributes to the inflammatory response by inducing recruitment of innate immune cells." (PMID 37359548, 2023). "Both IL-17A and IL-17F can generate homodimers or heterodimers and bind to heterodimeric IL-17RA and IL-17RC complexes, thereby activating downstream signaling transduction for host defense, autoimmune disease, or inflammation associated biological effects." (PMID 36274974, 2022). "Interleukin 17A and its receptor IL17RA play a pathogenic role in many inflammatory and autoimmune diseases, such as rheumatoid arthritis." (PMID 35082796, 2021). "IL-17RA signaling is implicated in both innate and adaptive elements of infectious and autoimmune diseases; however, little is known about its signaling in the CNS." (PMID 19400960, 2009). "Our study demonstrated that genetic variants in IL17RA and IL21R were associated with T1D susceptibility and that variants of IL-21R also predispose to other autoimmune diseases affecting thyroid and gastrointestinal tract tissues." (PMID 40979706, 2025). "IL‐17RA is the receptor for IL‐17A, which protects cells from invasion by pathogens and promotes pathological inflammation in autoimmune diseases." (PMID 39355508, 2024). "Our previous studies in patients with autoimmune diseases documented the important role of the SNPs located within genes coding for IL-17A, IL-17F cytokines as well as their IL-17RA and IL-17RC receptors." (PMID 38792460, 2024). "IL17RA KO mice are resistant to a number of autoimmune diseases including experimental autoimmune encephalomyelitis, collagen-induced arthritis, autoimmune glomerulonephritis, and spontaneous lupus in the BDX2 mouse model." (PMID 37691956, 2023). "To test the role of IL-17 in promoting autoimmune disease in Ets1 KO mice, we crossed Ets1 KO mice to IL-17 receptor A subunit (IL17RA) KO mice to generate double knockout (DKO) mice." (PMID 37691956, 2023). "Several studies showed the importance of IL-17A as a major cytokine that mediates responses in inflammation, infection, and autoimmune diseases through binding to its unique receptor (IL-17RA) and stimulates ACT1 signaling." (PMID 32650733, 2020). "Interleukin 17 (IL-17) and its cognate receptor A (IL-17RA) play a crucial role in Th17 cells-mediated pro-inflammatory pathway and pathogenesis of several autoimmune disorders including psoriasis." (PMID 30304852, 2018). "Authors attractively reported how preclinical and clinical studies have provided a solid scientific justification for targeting IL-17 and/or IL-17 receptor (IL-17RA) in human diseases such as inflammatory and autoimmune disorders." (PMID 27561214, 2016). "Given the important role that IL-17A plays in autoimmune diseases of the CNS, it is important to understand responses of CNS cells to IL-17RA signaling." (PMID 19400960, 2009). "To determine whether B cell-intrinsic IL-17RA signaling helps support the induction of self-directed and irrelevant antibodies, we repurposed a clinical assay used in the diagnosis of autoimmune diseases (antinuclear antibody or ANA)." (PMID 41335125, 2025).